KRT39 (keratin 39)
Description:
May play a role in late hair differentiation.
Synonyms: CK-39; K39; KA35
Tractability: No criterion of Open Targets' tractability assessment is met for any kind of drug.
Gene: Protein-coding gene on chromosome 17 (40,958,417 to 40,966,948, reverse strand). Ensembl gene ENSG00000196859.
Subcellular location (Human Protein Atlas): Annulus; Mid piece; Principal piece
Pathways (Reactome):
Developmental Biology: Formation of the cornified envelope; Keratinization
Gene Ontology:
Molecular function: protein binding; structural constituent of skin epidermis; structural molecule activity
Biological process: epithelial cell differentiation; intermediate filament organization; morphogenesis of an epithelium
Cellular component: cytoskeleton; cytosol; keratin filament
Genetic constraint (gnomAD): Loss-of-function variants: 45 observed, 52.36 expected, observed/expected ratio (o/e) 0.86, 90% interval 0.68 to 1.1. The upper end of that interval is the gene's LOEUF score, 1.1, which puts it in group 4 of 6, group 1 being the genes least tolerant of losing a copy. Missense variants: 572 observed, 618.89 expected, observed/expected ratio (o/e) 0.92, 90% interval 0.86 to 0.99. Synonymous variants: 207 observed, 237.82 expected, observed/expected ratio (o/e) 0.87, 90% interval 0.78 to 0.98.
Homologues: Orthologues: chimpanzee KRT39 (99% identical), macaque KRT39 (94% identical), rabbit KRT39 (77% identical), dog KRT39 (75% identical), pig KRT39 (75% identical), rat Krt39 (73% identical), mouse Krt39 (73% identical), guinea pig KRT39 (69% identical). Paralogues in human: KRT36 (52% identical), KRT32 (51% identical), KRT35 (50% identical), KRT31 (50% identical), KRT33A (49% identical), KRT33B (48% identical), KRT34 (48% identical), KRT40 (44% identical), KRT38 (43% identical), KRT37 (43% identical), KRT17 (39% identical), KRT14 (37% identical), and 56 more.
Diseases named in the same sentence as KRT39 in open-access papers:
KRT39 is named in the same sentence as 4 diseases in open-access papers, as found by Europe PMC text mining. Sharing a sentence is not in itself a finding about the gene and the disease.
KRT39 shares sentences with these, for which no sentence is quoted: leishmaniasis (4 papers); visceral leishmaniasis (3); infection (1); leprosy (1).